BDNF (brain derived neurotrophic factor)
Description:
Important signaling molecule that activates signaling cascades downstream of NTRK2. During development, promotes the survival and differentiation of selected neuronal populations of the peripheral and central nervous systems. Participates in axonal growth, pathfinding and in the modulation of dendritic growth and morphology. Major regulator of synaptic transmission and plasticity at adult synapses in many regions of the CNS. The versatility of BDNF is emphasized by its contribution to a range of adaptive neuronal responses including long-term potentiation (LTP), long-term depression (LTD), certain forms of short-term synaptic plasticity, as well as homeostatic regulation of intrinsic neuronal excitability. [Neurotrophic factor BDNF precursor form]: Important signaling molecule that activates signaling cascades downstream of NTRK2. Activates signaling cascades via the heterodimeric receptor formed by NGFR and SORCS2. Signaling via NGFR and SORCS2 plays a role in synaptic plasticity and long-term depression (LTD). Binding to NGFR and SORCS2 promotes neuronal apoptosis. Promotes neuronal growth cone collapse (By similarity).
Synonyms: ANON2; BULN2
Tractability: Antibody: UniProt places it where antibodies can reach, with high confidence; its Gene Ontology location is reachable by antibodies, with high confidence; UniProt predicts a signal peptide or a membrane-spanning region. PROTAC: ubiquitination databases record sites on it; a small molecule that binds it is known.
Target class: Secreted protein
Safety:
Unwanted effects reported when the protein is acted on. In parentheses: how it was acted on, where the effect was seen, and who reports it.
Impairment, Learning and memory (source: AOP-Wiki)
N/A, Neurodegeneration (source: AOP-Wiki)
respond to treatment for methamphetamine dependence (source: ClinPGx)
side effects (source: ClinPGx)
suicide ideation (source: ClinPGx)
weight gain (source: ClinPGx)
Gene: Protein-coding gene on chromosome 11 (27,654,893 to 27,722,058, reverse strand). Ensembl gene ENSG00000176697.
Subcellular location: Secreted; Secreted (Neurotrophic factor BDNF precursor form)
Pathways (Reactome):
Signal Transduction: Activated NTRK2 signals through CDK5; Activated NTRK2 signals through FRS2 and FRS3; Activated NTRK2 signals through FYN; Activated NTRK2 signals through PI3K; Activated NTRK2 signals through PLCG1; Activated NTRK2 signals through RAS; BDNF activates NTRK2 (TRKB) signaling; NTRK2 activates RAC1; PI5P, PP2A and IER3 Regulate PI3K/AKT Signaling; PIP3 activates AKT signaling
Disease: Constitutive Signaling by Aberrant PI3K in Cancer
Gene expression (Transcription): NPAS4 regulates expression of target genes
Gene Ontology:
Molecular function: protein binding; growth factor activity; nerve growth factor receptor binding; signaling receptor binding
Biological process: collateral sprouting; positive regulation of collateral sprouting; positive regulation of synapse assembly; synapse assembly; axon guidance; brain-derived neurotrophic factor receptor signaling pathway; cell surface receptor protein tyrosine kinase signaling pathway; modulation of chemical synaptic transmission; negative regulation of apoptotic signaling pathway; negative regulation of myotube differentiation; negative regulation of neuron apoptotic process; nerve development; nerve growth factor signaling pathway; nervous system development; neuron projection morphogenesis; positive regulation of brain-derived neurotrophic factor receptor signaling pathway; positive regulation of neuron projection development; regulation of protein localization to cell surface; circadian rhythm; trans-synaptic signaling by BDNF, modulating synaptic transmission
Cellular component: extracellular region; cytoplasm; endoplasmic reticulum lumen; perinuclear region of cytoplasm; synaptic vesicle; axon; cytoplasmic vesicle; dendrite; glutamatergic synapse; hippocampal mossy fiber to CA3 synapse; neuronal dense core vesicle; presynapse; secretory granule; secretory vesicle
Genetic constraint (gnomAD): Loss-of-function variants: 1 observed, 20.38 expected, observed/expected ratio (o/e) 0.0491, 90% interval 0.016 to 0.23. The upper end of that interval is the gene's LOEUF score, 0.23, which puts it in group 1 of 6, group 1 being the genes least tolerant of losing a copy. Missense variants: 195 observed, 334.08 expected, observed/expected ratio (o/e) 0.58, 90% interval 0.52 to 0.66. Synonymous variants: 100 observed, 128.23 expected, observed/expected ratio (o/e) 0.78, 90% interval 0.66 to 0.92.
Homologues: Orthologues: chimpanzee BDNF (100% identical), macaque BDNF (100% identical), pig BDNF (99% identical), dog BDNF (98% identical), mouse Bdnf (98% identical), rat Bdnf (98% identical), rabbit BDNF (96% identical), guinea pig BDNF (94% identical), tropical clawed frog bdnf (87% identical), zebrafish bdnf (77% identical). Paralogues in human: NTF4 (36% identical), NTF3 (36% identical), NGF (34% identical).
Diseases named in the same sentence as BDNF in open-access papers:
BDNF is named in the same sentence as 838 diseases in open-access papers, as found by Europe PMC text mining. Sharing a sentence is not in itself a finding about the gene and the disease. The quoted sentences say what the papers report.
depression (3,274 papers, 2004 to 2026). "Reduced levels of both GDNF and BDNF were linked to cognitive decline, with BDNF also decreased in PD patients with depression." (PMID 41697575, 2026). "Adult hippocampal neurogenesis persists throughout the human lifespan, yet declines in Alzheimer's disease and major depression, associated in part with reduced brain-derived neurotrophic factor (BDNF) levels." (PMID 42278308, 2026). "It has been established that BDNF is closely associated with depression, with lower BDNF levels correlating with more severe depressive symptoms, while increased serum BDNF levels were associated with improvements in depression." (PMID 41592015, 2026). "On one hand, reduced BDNF levels are implicated as a contributing factor to depression, as lower neurotrophic support leads to impaired synaptic function and neuronal atrophy." (PMID 40855004, 2026). "BDNF is well-established as a key player in neuroplasticity 45, and its reduction has been linked to depression." (PMID 40225589, 2025). "Reduced BDNF is associated with depression, while increased levels are necessary for antidepressant effects." (PMID 40108902, 2025). "Increased stress, which is a major risk factor for depression, reduces BDNF levels, specifically in brain regions involved in the regulation of mood, like the prefrontal cortex (PFC) and hippocampus." (PMID 40453264, 2025). "A growing body of evidence from both human and animal studies indicates that reduced BDNF expression in brain areas involved in emotion regulation—such as the hippocampus and prefrontal cortex—is a hallmark of depression." (PMID 41149800, 2025). "Reduced BDNF levels are associated with cognitive decline and increased susceptibility to depression, while increased BDNF promotes neuroplasticity and resilience." (PMID 41227125, 2025). "Individuals with depression exhibit reduced BDNF levels, highlighting its potential as a diagnostic biomarker." (PMID 40066336, 2025). "In conclusion, our findings indicate that SSRI-induced recovery from depression-like behaviors after mild bTBI is associated with the upregulation of 5-HT levels, pCREB and BDNF expression, and neurogenesis in the hippocampus." (PMID 40149758, 2025). "Given the high rate of BDNF Met carriage in individuals with depression and the established link between BDNF Met, thrombosis, and MI, it is highly likely to be a risk gene for post-depression MI." (PMID 41301929, 2025). "In the same way, this is the first study carried out in patients with MS that has found an association between the Val66Met polymorphism of the BDNF gene and depression." (PMID 40003622, 2025). "Other pathways, such as the mammalian target of rapamycin (mTORC1) signaling pathway and nuclear factor kappa-B (NF-κB), also play roles in BDNF-associated depression." (PMID 40003622, 2025). "Abnormal expression levels of functional proteins such as AMPAR-associated proteins (e.g., GluA1), postsynaptic dense protein 95 (PSD-95), CaMKII and BDNF, are strongly associated with susceptibility to depression." (PMID 40225589, 2025). "BDNF and its receptor TrkB are critical regulators of mood, with inhibition of BDNF signaling linked to anxiety and depression." (PMID 41163091, 2025). "Supporting this, animal studies show that BDNF deficiency exacerbates anxiety and depression‐like behaviours in females exposed to chronic unpredictable stress." (PMID 40222813, 2025). "The decline in BDNF levels is associated with depression and anxiety, which highlights the necessity for an enhancement in BDNF." (PMID 40094833, 2025). "Our findings suggest that elevated serum IL-1β levels and reduced BDNF levels are associated with an increased likelihood of developing depression." (PMID 40904969, 2025). "Some studies suggest an involvement of the BDNF, especially for the Val66Met polymorphism, in depression and PTSD among children and adolescents exposed to stressful life events; however, the findings remain inconsistent." (PMID 41300812, 2025).
depression (continued). "Decreasedserum BDNF levels are associated with a higher risk of depression, andantidepressant treatment can modulate these levels, thereby exertingantidepressant effects." (PMID 40352065, 2025). "Stress can influence BDNF expression, and alterations in BDNF levels have been implicated in stress-related disorders like depression and anxiety." (PMID 39911146, 2025). "Isorhamnetin can effectively restore the depletion levels of Nrf2, BDNF, and HO-1 in the cerebral cortex caused by LPS-induced depression, thus enhancing the therapeutic effect of the conventional antidepressant escitalopram." (PMID 41221044, 2025). "Low levels of BDNF are linked to depression and anxiety, whereas physical activity, which raises BDNF levels, can alleviate these symptoms." (PMID 40427596, 2025). "The brain-derived neurotrophic factor (BDNF) Val66Met gene polymorphism is an innate factor that influences the interplay between depression, thrombosis, and CVD risk." (PMID 41301929, 2025). "Second, depression-associated inflammatory markers, such as IL - 1β, exhibit significant variability across populations and are influenced by regulatory factors like BDNF, undermining their reliability as universal biomarkers." (PMID 41000397, 2025). "BDNF is also reduced in conditions like diabetes and smoking, both independent depression risk factors." (PMID 40428308, 2025). "Both insomnia and depression are usually associated with lower serum BDNF levels in most studies, but their relationship with neuroinflammation in these patients remains poorly understood." (PMID 41465566, 2025). "Both preclinical and clinical studies have implicated impaired BDNF signaling through its TrkB receptor in the pathophysiology of mood disorders, including depression." (PMID 40003622, 2025). "These BDNF polymorphisms have been shown to be related to various mood disorders, including depression." (PMID 41311851, 2025). "Previous studies have shown that BDNF gene SNPs are associated with various psychiatric disorders, including major depressive disorder, bipolar disorder, schizophrenia and even suicidal behaviour." (PMID 40767639, 2025). "BDNF is essential for neurons' survival, growth, and plasticity, with higher levels associated with better mental health and reduced vulnerability to depression." (PMID 39981404, 2025). "Further, researchers discovered that variations in both SERT and BDNF genes modify the risk of depression conferred by childhood maltreatment when analyzed together." (PMID 41011229, 2025). "Multivariate analysis identified PD-1 (OR = 3.32) and MMP-9 (OR = 2.18) as independent risk factors for depression, while IL-10 (OR = 0.62) and BDNF (OR = 0.12) emerged as protective factors." (PMID 40823578, 2025). "The antidepressant effects of drugs are also associated with activation of the CREB/BDNF signaling pathway in mice with depression." (PMID 40149758, 2025). "Stress-related downregulation of BDNF has been linked to neurodegenerative processes and has been proposed as a key mediator in the etiology of mood disorders such as depression." (PMID 39896238, 2025). "While exercise-induced increases in BDNF are associated with improvements in symptoms like fatigue and depression, its role as a mechanistic biomarker linking BDNF changes to symptom improvement remains inconsistent." (PMID 40002745, 2025). "Since our previous studies showed an association of the functional SNP rs6265 in the BDNF gene with depression and response to therapy, we decided to extend the investigation and test additional SNPs in the BDNF gene, NGF, and NRG1." (PMID 40869303, 2025). "The BDNF Val66Met polymorphism significantly interacts with childhood adversity and stressful life events, contributing to the development of depression." (PMID 40003622, 2025). "For example, expression of brain-derived neurotrophic factor (BDNF) is often reduced in the context of depression, and this reduction has been linked to altered astrocyte function." (PMID 40305200, 2025).
depression (continued). "BDNF plays a key role in neuroprotection and neuroplasticity, and its low levels are associated with the occurrence of depression and cognitive function decline." (PMID 40821647, 2025). "On the other hand, ultra-processed, nutrient-poor diets are associated with lower BDNF levels and a higher risk of depression." (PMID 40871684, 2025). "In further support, some years later, an association between low BDNF plasma levels and major depression was being repeatedly reported." (PMID 40002450, 2025). "Currently, no studies have been published analyzing the relationship between the Val66Met polymorphism of the BDNF gene and MS in Latin American populations, let alone its association with depression." (PMID 40003622, 2025). "The effects of some strains have been associated with an increased expression of hippocampal BDNF on anxiety and depression in different protocols in mice treated with Clostridium NCIMB 43454 (KR20220119055A) for six days." (PMID 40342368, 2025). "Brain-derived neurotrophic factor (BDNF) is closely associated with clinical changes in depression, as indicated by meta-analyses linking BDNF levels to depressive disorders." (PMID 40177374, 2025). "Vitamin D promotes BDNF expression in the hippocampus, enhancing neuroplasticity and reducing depression recurrence risk." (PMID 41170359, 2025). "The Met allele, associated with reduced BDNF availability, is therefore considered a risk factor for psychopathology, including higher neuroticism and anxiety, depression and suicide risk." (PMID 40806241, 2025). "The onset of depression has been associated with structural changes in the hippocampus and a decrease in BDNF, GDNF, and NGF." (PMID 40260589, 2025). "In contrast, p62 deficiency resulted in anxiety, depression, and a loss of working memory, accompanied by decreased serum brain-derived neurotrophic factor (BDNF) levels." (PMID 40497971, 2025). "Higher BDNF levels are often associated with improved cognitive function, while lower levels are linked to conditions such as depression and neurodegenerative diseases." (PMID 40002745, 2025). "Preclinical studies have consistently demonstrated that alterations in the tPA/BDNF pathway are implicated in the pathogenesis of depression." (PMID 40725146, 2025). "It has been well demonstrated that the downregulation/dysregulation of the BDNF/TrkB system is implicated in the pathogenesis of neurologic and psychiatric disorders, such as Alzheimer’s disease (AD) and depression." (PMID 40005159, 2025). "Neurotrophic factors like BDNF are crucial for preventing cellular atrophy and neuronal loss in depression, and individuals with depression typically show lower BDNF levels (Jones and Reichardt 1990; Banasr, Dwyer, and Duman 2011)." (PMID 40177327, 2025). "Epigenetic studies show that chemical silencing of BDNF (via hypermethylation) is also strongly associated with depression in patients with epilepsy." (PMID 40941042, 2025). "Oxidative stress and inflammation play an important pathogenic role in the interaction of diabetes and depression, which provides a feasible explanation of the role of diabetes in changes in serum concentrations of BDNF (Correia, Cardoso & Vale, 2023)." (PMID 41142318, 2025). "A review of 103 meta-analyses classified both low 25(OH)D and reduced peripheral BDNF levels as possible risk factors for depression, but downgraded the quality of evidence to low due to cross-sectional heterogeneity." (PMID 40871684, 2025). "It has been demonstrated that altered expressions of BDNF and/or TrkB are associated with major depressive disorder (MDD)." (PMID 40005159, 2025). "Human studies have subsequently shown that low serum and plasma BDNF levels are associated with depression and anxiety." (PMID 41424669, 2025).